MCTS2 (MCTS family member 2)
Synonyms: psiMCT-1; MCTS2P
Gene: Protein-coding gene on chromosome 20 (31,547,379 to 31,569,541, forward strand). Ensembl gene ENSG00000101898.
Subcellular location: Cytoplasm
Subcellular location (Human Protein Atlas): Cytosol; Plasma membrane
Gene Ontology:
Molecular function: RNA binding
Biological process: formation of translation preinitiation complex; translation reinitiation
Cellular component: cytoplasm
Homologues: Orthologues: tropical clawed frog mcts1 (92% identical), zebrafish mcts1 (90% identical), Caenorhabditis elegans C11D2.7 (62% identical), Drosophila melanogaster MCTS1 (59% identical). Paralogues in human: MCTS1 (95% identical).
Diseases named in the same sentence as MCTS2 in open-access papers:
MCTS2 is named in the same sentence as 6 diseases in open-access papers, as found by Europe PMC text mining. Sharing a sentence is not in itself a finding about the gene and the disease. The quoted sentences say what the papers report.
cancer (3 papers, 2011 to 2021). A tumor composed of atypical neoplastic, often pleomorphic cells that invade other tissues. "Considering that Mcts2 is subject to genomic imprinting, as is Mcts2, potential disruption of the imprinting mechanism at the Mcts2 locus could have major consequences for cancer development if Mcts2 is shown to be an oncogene." (PMID 21166792, 2011). "For example, the four imprinted regions on chromosome 20q (MCTS2, NNAT, L3MTBL1 and GNAS) were invariable subject to copy-number gains with very few deletions observed in the four cancer types." (PMID 28883545, 2017).
tumor (2 papers, 2013 to 2018). "The following DMRs showed aberrant methylation in only one tumor: ARH1-CG1, NAP1L5-DMR, PEG10-DMR, H19 promoter, WT1-AS-DMR, MEG3-CG7-DMR, MCTS2-DMR, NESP-DMR, and GNAS1A-DMR." (PMID 24373183, 2013).
MCTS2 also shares sentences with these, for which no sentence is quoted: breast tumors (1 paper); hepatocellular carcinoma (1); lung carcinoma (1); ovarian carcinoma (1).